HDAC1 (histone deacetylase 1)
Diseases named in the same sentence as HDAC1 in open-access papers (continued):
Sharing a sentence is not in itself a finding about the gene and the disease.
Obesity (11 papers, 2019 to 2025). Accumulation of substantial excess body fat. "Specifically, it is confirmed that HDACi specifically targets HDAC1 and promotes the H3K27ac modification of fat mass‐ and obesity‐associated gene (FTO) and AlkB Homolog 5, RNA Demethylase (ALKBH5), which results in significant activation of FTO and ALKBH5." (PMID 39888307, 2025). "Obesity-induced hypertension is associated with increased levels of histone deacetylase 1 and acetylated histone H3 in mice fed a high-fat diet." (PMID 35571911, 2022). "Following the association between ATF3 and HDAC1, whether obesity is also reduced through the NF-κB pathway and adipogenesis/adipogenesis-targeted genes are regulated by NF-κB will be assessed in future work." (PMID 35326476, 2022). "Previous research has shown that high expression levels of HDAC1 were correlated with obesity and overweight in HFD-fed mice, while there was also a study showing the expression of HDAC1 in adipose tissues from obese women was lower in comparison with normal-weight individuals." (PMID 38832038, 2024). "We also performed pathway analysis using another database (REACTOME), and found that HDAC1 is shared between both databases (KEGG and REACTOME), suggesting obesity-associated dysregulation of HDAC1-related signaling pathways (data not shown)." (PMID 31015518, 2019). "In mouse adipocytes, it was shown that TET1 coordinates with histone deacetylase 1 (HDAC1) to epigenetically suppress thermogenic gene transcription and that adipocyte-specific Tet1 knockout in mice increases energy expenditure and protects against diet-induced obesity and insulin resistance." (PMID 38216792, 2024). "TNF-α downregulated some of the DNA damage repair genes, which are also altered by obesity: PARP1 (−49.3%, P = 0.008), BLM (−46.9%, P = 0.02), FEN1 (−25.5%, P = 0.04), and PCNA (−38.0%, P = 0.008), but did not affect HDAC1 and Ku70 gene expression." (PMID 39092995, 2024). "Taken together, these results suggest that HDAC3 inhibition rather than HDAC1/2 inhibition by MS-275 protects against lipotoxicity in C2C12 myotubes and skeletal muscle, and may be effective for the treatment of obesity and insulin resistance." (PMID 33362555, 2020).
Stroke (10 papers, 2018 to 2026). Sudden impairment of blood flow to a part of the brain due to occlusion or rupture of an artery to the brain. "HDAC1 inhibition exacerbated stroke outcomes, increasing infarct volume, neuronal loss, and reactive oxygen species (ROS) production." (PMID 41388741, 2025). "Network pharmacology analysis revealed eight intersecting targets, including MAPK1, PRKCB, HDAC1, and serotonin receptors, associated with neuroinflammatory and vascular pathways in strokes." (PMID 41011194, 2025). "In the present study, we found that the inhibition of HDAC1 exacerbates neuronal loss and increases the infarct volume in stroke." (PMID 34381129, 2021). "We found that HDAC1 inhibition promoted the infarct volume, neuronal loss, DNA damage, neuronal apoptosis after stroke, and levels of reactive oxygen species and inflammation cytokines." (PMID 34381129, 2021). "Accordingly, our findings further support the essential role of HDAC1 in stroke pathogenesis; HDAC1 inhibition aggravates neuronal loss and motor function deficits." (PMID 34381129, 2021). "Therefore, we further investigated NF-κB–associated signalling to elucidate its role in HDAC1-mediated neuroinflammatory responses following stroke." (PMID 41388741, 2025). "However, the mechanisms underlying the role of HDAC1 in stroke pathogenesis are still controversial." (PMID 34381129, 2021). "To understand how HA has a neuroprotective effect on the ischemic brain, we further examined the DNA damage level in cerebral ischemia rats with immunofluorescent staining for NeuN and γH2AX to validate the underlying HDAC1-mediated mechanism in stroke pathogenesis." (PMID 34638996, 2021). "Thus, restoration of HDAC1 enzymatic activity was shown to elicit a neuroprotective effect in preventing neuronal loss after a stroke." (PMID 34638996, 2021). "To confirm whether HDAC1 dysfunction exacerbates neuronal loss after stroke, we examined the survival of neurons in the brain within ischemic core and penumbra regions on day 3 after stroke." (PMID 34381129, 2021). "In this case, HDAC1 inhibition by MS-275 was detrimental and exacerbated gliosis in both astrocytes and microglia, further supporting HDAC1-mediated neuroprotection in stroke." (PMID 41566325, 2026). "To assess the role of HDAC1 in microglial activation following ischemic stroke, we adopt a rat stroke model of endothelin-1 injection and performed HDAC1 knock down in the cerebral cortex by concurrently stereo-microinjection of endothelin-1 and HDAC1 siRNA." (PMID 41388741, 2025). "Collectively, these findings reframe HDAC1 as a function molecule in the post-stroke brain—one that preserves neuronal viability through genome maintenance and simultaneously restrains innate immune activation through epigenetic repression of NF-κB signalling." (PMID 41388741, 2025). "HDAC1 contributes to axonal regeneration and neuronal survival post-stroke, often through epigenetic mechanisms." (PMID 41011194, 2025). "Quantification of CD3+ cells confirmed this trend, with a significant increase in CD3+ cell density in the Stroke + HDAC1 KD group relative to both the Sham and Stroke groups (p < 0.05)." (PMID 41388741, 2025). "In this study, we investigate the role of HDAC1 in microglial phenotypic transitions and its impact on stroke-induced neuroinflammation." (PMID 41388741, 2025). "Neuroinflammation after stroke is highly dynamic, and the timing of analysis is critical for interpreting the role of HDAC1 in this process." (PMID 41388741, 2025). "To assess the impact of HDAC1 knockdown on T-cell recruitment, we performed immunofluorescence staining for CD3, a marker of T lymphocytes, in Sham, Stroke and Stroke + HDAC1 KD groups." (PMID 41388741, 2025). "To assess the extent of cellular injury, we measured LDH levels, which were significantly elevated following stroke and further increased in the Stroke + HDAC1 KD group (p < 0.01)." (PMID 41388741, 2025).
Stroke (continued). "This increase was further exacerbated in the Stroke + HDAC1 KD group (p < 0.01)), suggesting that HDAC1 knockdown promotes extracellular matrix degradation, which is associated with increased blood-brain barrier (BBB) permeability and neuronal damage." (PMID 41388741, 2025). "Our previous study demonstrated that HDAC1 inhibition at 24 h after stroke exacerbated gliosis and elevated IL-1β and TNF-α, underscoring its importance in the acute phase." (PMID 41388741, 2025). "HDAC1 acts as a key repressor of NF-κB–driven pro-inflammatory microglial activation and neuroinflammation in stroke." (PMID 41388741, 2025). "HDAC1 enzymatic reactivation by compound 5104434 promotes functional recovery and suppresses NF-κB–driven microglial activation after stroke." (PMID 41388741, 2025). "The results suggest that HDAC1 participates in neuroprotection and affects behavioral outcomes in stroke." (PMID 34381129, 2021). "Overall, our results indicate that HDAC1 was deregulated after stroke, implying its involvement in the pathogenesis of brain ischemia." (PMID 34381129, 2021). "We evaluated the levels and activity of HDAC1 after stroke as well as its involvement in DNA damage, neuronal apoptosis, reactive oxygen species (ROS), inflammation cytokines, and behavioral outcomes after brain ischemia." (PMID 34381129, 2021). "To understand the effect of HDAC1 in pathologic mechanism of stroke, we examined the levels of ROS, LDH, IL-1β, and TNF-α on day 3 after stroke." (PMID 34381129, 2021). "Comparing to the current study, we support the essential role of HDAC1 in the modulation of neuron viability, and we additionally provide a selective evaluation of HDAC1 in stroke pathogenesis." (PMID 34638996, 2021). "We observed that the neurological severity score and cylinder behavior both deteriorated after HDAC1 dysfunction in stroke." (PMID 34381129, 2021). "HDAC1i MS-275 was used to dominantly inhibit the function of HDAC1 in order to elucidate the roles of HDAC1 in stroke pathogenesis." (PMID 34381129, 2021). "Our previous data showed that the protein level and enzymatic activity of HDAC1 are deregulated in stroke pathogenesis." (PMID 34638996, 2021). "Remarkably, our recent findings showed that the levels of HDAC1 and its enzymatic activity are decreased in stroke pathogenesis." (PMID 34638996, 2021). "Due to the specificity of HDAC1 activation and security of drug toxicity confirmed in the current study and our previous work, a sufficient drug for stroke therapy is still an unmet medical need." (PMID 34638996, 2021). "To characterize the role of HDAC1 in ischemic pathogenesis, we first performed Western blotting to evaluate the expression levels of HDAC1 in the ischemic brain region on day 1 after stroke onset." (PMID 34381129, 2021). "Our results revealed that HDAC1 was deregulated following stroke, and its expressional level and enzymatic activity were decreased." (PMID 34381129, 2021). "To evaluate the effect of HDAC1 in stroke pathogenesis, we examined the infarct volume in our brain ischemic rat model." (PMID 34381129, 2021). "The result indicated that HDAC1 activity was repressed by ischemic insult; reduced HDAC1 activity was identified in the rat brain at 24 and 72 h after stroke." (PMID 34381129, 2021). "Mature OLs showed a retained increase of HDAC2 following stroke, while HDAC1 levels were decreased, indicating that individual HDACs family members play distinct roles during recovery after stroke." (PMID 31614602, 2019). "Additionally, oxidative stress, measured by H2O2 production, followed a similar trend, with significantly increased ROS levels in the Stroke group and an even greater surge in the Stroke + HDAC1 KD group (p < 0.001)." (PMID 41388741, 2025). "We hypothesize that impaired HDAC1 function exacerbates post-stroke inflammation by shifting microglia towards a pro-inflammatory state, thereby worsening neurological outcomes." (PMID 41388741, 2025).
Stroke (continued). "To investigate the role of HDAC1 in microglial polarization following ischemic stroke, we examined the expression of pro-inflammatory and anti-inflammatory microglial markers in brain sections from Sham, Stroke, and Stroke + HDAC1 KD groups 3 days after brain ischemia induction." (PMID 41388741, 2025). "Thus, HDAC1 deregulation is crucial in stroke pathogenesis, and the compound 5104434 possesses therapeutic potential in attenuating brain damage and brain functionality loss." (PMID 34638996, 2021). "Due to the role of HDAC1 in stroke pathogenesis being largely unknown, we examined the interplay of HDAC1 and evaluated the therapeutic potential of compound 5104434 in stroke treatment." (PMID 34638996, 2021). "It suggests that HDAC1 is essential in secondary brain injury of stroke." (PMID 34381129, 2021). "Our data indicated that HDAC1 is essential in stroke and is involved in DNA damage and cell apoptosis during ischemic pathogenesis, supporting HDAC1 as a specific target for developing stroke therapy." (PMID 34381129, 2021). "In this study, we determined that HDAC1 is deregulated in stroke pathogenesis." (PMID 34381129, 2021). "A novel compound named 5104434 exhibits efficacy to selectively activate HDAC1 enzymatic function in neurodegeneration, but its potential in stroke therapy is still unknown." (PMID 34638996, 2021). "Furthermore, the data showed MS-275 significant repressed HDAC1 enzymatic activity that further inhibited HDAC1 function in ischemic brain of rats at 24 and 72 h after stroke." (PMID 34381129, 2021). "In the present study, we further characterized the role of HDAC1 in stroke pathogenesis." (PMID 34638996, 2021). "Therefore, we investigated the role of HDAC1 in stroke by using a rat model of endothelin-1-induced brain ischemia." (PMID 34381129, 2021). "In conclusion, our study showed that HDAC1 deregulation is involved in stroke pathogenesis." (PMID 34638996, 2021). "Subsequently, to determine the enzyme activity of HDAC1 on day 1 and 3 after stroke onset, we immunoprecipitated HDAC1 in brain lysates obtained from the core and penumbra segmental region; we conducted enzyme activity assay for HDAC1 with equal HDAC1 concentration from the sham and stroke groups." (PMID 34381129, 2021). "In the pathogenesis of stroke, we found that HDAC1 levels and activity are reduced by ET-1." (PMID 34381129, 2021). "Notably, this reduction was also marked in the Stroke + HDAC1 KD group." (PMID 41388741, 2025). "Our recent findings suggest that HDAC1 dysfunction drives microglial reactivation, aggravating neuroinflammation and blood-brain barrier (BBB) disruption in stroke." (PMID 41388741, 2025). "Eight common genes were found across all three compounds and stroke: MAPK1, PRKCB, PRKCG, HDAC1, HTR1A, HTR2A, HTR2C, and HTR7." (PMID 41011194, 2025). "However, how HDAC1 regulates motor and sensory behaviors in stroke remains unclear." (PMID 34381129, 2021). "Notably, STAT3 activation in our study appeared more pronounced in HDAC1 KD + IFN-γ group than that HDAC1 KD only and Stroke + IFN-γ groups." (PMID 41388741, 2025). "Furthermore, since HDAC1 and 2, belonging to class I HDACs, and HDAC4 and 5, belonging to class II HDACs, increase in an in vitro model of stroke 30, 39, we investigate the specificity of HDAC9, among HDACs isoforms, in the modulation of TfR1 and GPX4 after ODG/Rx." (PMID 37324938, 2023). "Moreover, to understand the effect of MS-275 in HDAC1 level, we evaluated the level of HDAC1 at 24 and 72 h after stroke, the data showed stroke induced a lower HDAC1 level comparing to sham rats, whereas MS-275 did not significantly reduce HDAC1 level in rats with stroke." (PMID 34381129, 2021). "In contrast, inhibition at two weeks post-stroke did not significantly affect BBB integrity or neuroinflammation, suggesting a time-dependent contribution of HDAC1." (PMID 41388741, 2025).
Stroke (continued). "Consistent with the notion that HDAC2 is a critical factor in EE-mediated stroke recovery 36, HDAC2 but not HDAC1 knockdown upregulated GAT-1 expression." (PMID 33664860, 2021).
triple-negative breast carcinoma (10 papers, 2018 to 2026). An invasive breast carcinoma which is negative for expression of estrogen receptor (ER), progesterone receptor (PR), and human epidermal growth factor receptor 2 (HER2). "We asked whether sumoylated SnoN suppression of EMT in cancer cells is mediated by regulation of HDAC1 and/or p300 in the human triple negative breast cancer MDA-MB-231 cells." (PMID 37414747, 2023). "In triple-negative breast cancer (TNBC), hypoxia disrupts immune function by engaging HIF-1α with histone deacetylase 1 (HDAC1) and polycomb repressive complex 2 (PRC2), leading to suppression of T and NK cell activity." (PMID 41200166, 2025). "Meta-analyses of gene expression showed a significant reduction in HDAC1 and HDAC2 expression in triple-negative breast cancer samples." (PMID 40375313, 2025). "These two compounds have IC50 values for HDAC1 and HDAC2 higher than 10 μM, and compound 6 showed in vitro efficacy in suppressing the cancer stem cell subpopulation of triple-negative breast cancer by downregulating β-catenin." (PMID 29498635, 2018).
depression (9 papers, 2018 to 2025). "In the chronic social stress defeat model of depression, low endothelial levels of FoxO1 and HDAC1 are associated with stress resilience." (PMID 33139732, 2020). "Additionally, exifone-induced alterations in mTOR/Akt/PI3k signaling and eEF2 activity further supported HDAC1 in the synaptogenesis associated with neuroinflammation-induced depression." (PMID 33526073, 2021). "Exifone, a selective HDAC1 activator, reversed the antidepressant and anti-inflammatory effects of fluoxetine both in vivo and in vitro, supporting a causing role of HDAC1 in neuroinflammation allied depression." (PMID 33526073, 2021). "Here, we demonstrated that apart from inhibiting neuroinflammation, fluoxetine could restore HDAC1-eEF2 activity (phosphorylation), which eventually reversed synaptogenic loss and depression-like phenotypes." (PMID 33526073, 2021). "Our findings supported a significant role of HDAC1 signaling in the pathophysiology of neuroinflammation-related depression." (PMID 33526073, 2021). "We investigated the involvement of HDAC1 and eEF2 in the antidepressant mechanisms of fluoxetine using a lipopolysaccharide (LPS)-induced depression-like behavior model." (PMID 33526073, 2021). "It has been reported that HDAC1 is involved in fluoxetine-mediated antidepressant mechanism in the LPS-induced depression mouse model." (PMID 35126089, 2021). "Mice treated with LPS displayed depression-like behaviors, pronounced neuroinflammation, increased HDAC1 expression, and reduced eEF2 activity, as accompanied by altered synaptogenic factors including BDNF, SNAP25, and PSD95." (PMID 33526073, 2021). "Elevated HDAC1 activity also promotes the polarization of microglia toward a pro-inflammatory phenotype, thereby strengthening the link between the inflammatory microenvironment and depression-like behaviors." (PMID 40949123, 2025). "Similarly, we have previously reported the role of HDAC1 in lipopolysaccharide-induced neuroinflammation and depression models." (PMID 37005686, 2023). "Depression with high levels of TNF-α stimulates NF-κB, then elevates histone deacetylase 1 activity and represses claudin-5 expression, resulting in loss of tight-junction proteins and disruption of blood-brain barrier." (PMID 38459460, 2024). "Although HDACs inhibition reduces inflammatory responses evoked by inflammatory agents like LPS, and altered HDACs including HDAC1 expression has been reported in the brain of patients with MDD, the exact roles of HDACs in neuroinflammation and depression are still largely unknown." (PMID 33526073, 2021).